PDLIM2 (PDZ and LIM domain 2)
Description:
Probable adapter protein located at the actin cytoskeleton that promotes cell attachment. Necessary for the migratory capacity of epithelial cells. Overexpression enhances cell adhesion to collagen and fibronectin and suppresses anchorage independent growth. May contribute to tumor cell migratory capacity.
Synonyms: MYSTIQUE; SLIM
Tractability: PROTAC: its protein half-life has been measured.
Gene: Protein-coding gene on chromosome 8 (22,578,058 to 22,598,025, forward strand). Ensembl gene ENSG00000120913.
Subcellular location: Cytoplasm; Nucleus; Cytoplasm, cytoskeleton (Isoform 1); Cytoplasm, cytoskeleton (Isoform 2); Nucleus (Isoform 3)
Subcellular location (Human Protein Atlas): Actin filaments; Focal adhesion sites
Gene Ontology:
Molecular function: protein binding; actin binding; muscle alpha-actinin binding; ubiquitin protein ligase binding
Biological process: actin cytoskeleton organization; heart development; muscle structure development; protein catabolic process
Cellular component: actin cytoskeleton; focal adhesion; adherens junction; filamentous actin; stress fiber; Z disc; cytoplasm; cytoskeleton; nucleus
Genetic constraint (gnomAD): Loss-of-function variants: 53 observed, 42.83 expected, observed/expected ratio (o/e) 1.24, 90% interval 0.99 to 1.56. The synonymous counts are far from expectation, so gnomAD's model fits this gene poorly and the ratio says little. Missense variants: 912 observed, 726.93 expected, observed/expected ratio (o/e) 1.25, 90% interval 1.19 to 1.33. Synonymous variants: 398 observed, 308.68 expected, observed/expected ratio (o/e) 1.29, 90% interval 1.19 to 1.4.
Homologues: Orthologues: chimpanzee PDLIM2 (99% identical), macaque PDLIM2 (98% identical), dog PDLIM2 (85% identical), pig PDLIM2 (83% identical), rabbit PDLIM2 (82% identical), mouse Pdlim2 (79% identical), rat Pdlim2 (78% identical), zebrafish pdlim2 (46% identical), guinea pig Pdlim2 (33% identical), Caenorhabditis elegans alp-1 (25% identical), tropical clawed frog pdlim2 (22% identical), Drosophila melanogaster Zasp52 (19% identical). Paralogues in human: PDLIM1 (32% identical), PDLIM4 (32% identical), PDLIM3 (28% identical), LDB3 (23% identical), PDLIM7 (21% identical), PDLIM5 (20% identical), PRICKLE4 (12% identical).
Diseases named in the same sentence as PDLIM2 in open-access papers:
PDLIM2 is named in the same sentence as 96 diseases in open-access papers, as found by Europe PMC text mining. Sharing a sentence is not in itself a finding about the gene and the disease. The quoted sentences say what the papers report.
lung carcinoma (13 papers, 2018 to 2025). "For example, lung epithelial- or myeloid-specific PDLIM2 deletion or global PDLIM2 deletion in mice promotes lung cancer development, chemoresistance, and/or causes complete resistance to immune checkpoint inhibitors (ICIs)." (PMID 41346604, 2025). "Human and mouse studies demonstrate PDLIM2 repression as a causative driver of lung cancer and therapy resistance." (PMID 41346604, 2025). "In this study, we focused on lung cancer to investigate the function and mechanism of PDLIM2 in tumor growth as lung cancer is the leading cause of cancer-related deaths, and there is an unmet need for its treatment." (PMID 38880883, 2024). "Collectively, these findings demonstrate that reduced expression of PDLIM2 is associated with lung cancer progression." (PMID 38880883, 2024). "Downregulation of PDLIM2 in lung cancer cells was highly associated with increased NF-κB activation and dysregulated expression of genes for mitochondrial function." (PMID 38880883, 2024). "We believe that these knowledges are applicable to other cancers, because PDLIM2 repression has also been linked to numerous human cancers other than lung cancer." (PMID 39718207, 2024). "In this study, we investigated the role and underlying mechanisms of PDLIM2 in regulating lung cancer growth." (PMID 38880883, 2024). "(F) qPCR showing PDLIM2 loss in human lung cancer cell lines with known copy number of the PDLIM2 gene (n=25)." (PMID 39718207, 2024). "In mouse, inhibition of PDLIM2 resulted in increased lung cancer incidence and was reported to cause resistance against anticancer drugs and immunotherapeutic drugs, such as PD-1 blockers." (PMID 35707002, 2022). "In mice, the inhibition of PDLIM2 resulted in increased lung cancer incidence and was reported to cause resistance against anticancer drugs and immunotherapeutic drugs, such as PD-1 inhibitor." (PMID 34203785, 2021). "Further, we found that PDLIM2 was decreased in lung macrophages by oxidative stress–activated transcription repressor BTB and CNC homology 1 (BACH1), and that PDLIM2 repression was associated with poor survival of patients with lung cancer." (PMID 33539325, 2021). "PDLIM2 in AMs is repressed during lung tumorigenesis and PDLIM2 repression is associated with poor survival of patients with lung cancer." (PMID 33539325, 2021). "To investigate the pathogenic and clinical relevance of AM PDLIM2 in lung cancer, we first examined its expression in bronchioalveolar lavage (BAL) cells, of which 90%–95% are AMs, from urethane-treated mice." (PMID 33539325, 2021). "To investigate the pathogenic and clinical significance of PDLIM2 in human lung cancer, we analyzed PDLIM2 expression in human lung cancers using The Cancer Genome Atlas (TCGA) database." (PMID 31757943, 2019). "Additional mechanism underlying lung cancer chemoresistance and in particular paclitaxel resistance by PDLIM2 repression involves induction of the multi-drug resistance gene MDR1." (PMID 31757943, 2019). "This NanoPDLIM2-based combination therapy may be effective for treating other cancers, since PDLIM2 repression has also been linked to numerous human cancers other than lung cancer." (PMID 40948895, 2025). "In this study, we investigated the pro-tumoral effect of PDZ and LIM domain 2 (PDLIM2) downregulation in lung cancer growth and its association with the accumulation of mitochondrial ROS, oncometabolites and the activation of hypoxia-inducible factor-1 (HIF-1) α in the process." (PMID 38880883, 2024). "In addition, PDLIM2 expression was inversely associated with the carboplatin sensitivity of lung cancer cells." (PMID 31757943, 2019). "One main mechanism underlying PDLIM2 suppression of lung cancer development and therapeutic resistance involves repressing STAT3-dependent transcriptional repression of MHC-I and subsequent tumor immune evasion in the presence or absence of anti-PD-1 and chemotherapeutic drugs." (PMID 31757943, 2019).
lung carcinoma (continued). "While PDLIM2 is epigenetically repressed in human lung cancer, associating with therapeutic resistance and poor prognosis, its global or lung epithelial-specific deletion in mice causes increased lung cancer development, chemoresistance, and complete resistance to anti-PD-1 and epigenetic drugs." (PMID 31757943, 2019). "Notably, PDLIM2 is frequently repressed in lung tumors through both genetic loss and epigenetic silencing, with loss of heterozygosity and/or promoter methylation observed in over 90% of lung cancer patients." (PMID 40948895, 2025). "While PDLIM2 is epigenetically repressed in human lung cancer, associating with therapeutic resistance and poor prognosis, its global or lung epithelial-specific deletion in mice leads to lung cancer development, chemoresistance, and complete resistance to anti-PD-1 and epigenetic drugs." (PMID 39718207, 2024). "Moreover, PDLIM2 suppression by reactive oxygen species (ROS) in alveolar macrophages has been associated with the polarization/activation of pro-tumourigenic macrophages in lung cancer." (PMID 36531051, 2022). "Interestingly, chemo and epigenetic drugs induce PDLIM2-independnet PD-L1 expression on lung cancer and associated macrophages, providing a different mechanism underlying lung cancer resistance to the conventional chemotherapy and potentially new epigenetic therapy." (PMID 31757943, 2019). "In this study, we employed a large panel of human lung tissue samples and cell lines as well as publically available big data to examine whether and how PDLIM2 is deregulated in human lung cancer and the pathogenic and clinical relevance of PDLIM2 deregulation." (PMID 31757943, 2019). "This protocol provides a reproducible platform to investigate the translational potential of restoring PDLIM2 expression to overcome therapeutic resistance and enhance immune responses in lung cancer." (PMID 40948895, 2025). "PDLIM2, a PDZ-LIM domain-containing protein, is a tumor suppressor implicated in the pathogenesis of various cancers, and particularly, lung cancer." (PMID 40948895, 2025). "As a matter of fact, they are the first investigation on the role of PDLIM2 in the lung diseases other than lung cancer." (PMID 41346604, 2025). "Recent studies indicate that PDLIM2 repression in the lung macrophages of mice with lung cancer is attributed to the transcription repressor BACH1 activated by reactive oxygen species (ROS)." (PMID 41346604, 2025). "Recent studies identify the PDZ-LIM domain-containing protein PDLIM2 as a key molecular checkpoint in preventing lung cancer, COPD, and ILD/PF." (PMID 41000764, 2025). "We found that the gene expression of PDLIM2 was downregulated in lung cancer and correlated with a poor prognosis in lung cancer patients." (PMID 38880883, 2024). "Upon analyzing gene expression profiles in parental and PDLIM2 knockdown lung cancer cells, we observed a significant impact of PDLIM2 downregulation on the expression of genes involved in mitochondrial functions." (PMID 38880883, 2024). "In breast, colorectal, and lung cancers, PDLIM2 expression is epigenetically suppressed at the transcriptional level or regulated by microRNAs posttranscriptionally." (PMID 38880883, 2024). "Our analysis indicate that PDLIM2 repression in human lung cancer involves both genetic deletion and epigenetic alteration." (PMID 39718207, 2024). "Like its human counterpart, the murine lung cancer induced by urethane also shares PDLIM2 repression, in addition to their similarities in histology, genetics, molecular biology, and immunology." (PMID 39718207, 2024). "We previously identified the PDZ-LIM domain-containing protein 2 (PDLIM2) as a bona fide tumor suppressor that is repressed in lung cancer to drive cancer and its chemo and immunotherapy resistance, suggesting a new target for lung cancer therapy improvement." (PMID 39718207, 2024).
lung carcinoma (continued). "Our analysis further revealed that PDLIM2 knockdown in lung cancer cells altered the expression of genes across various enzyme complexes in the TCA cycle." (PMID 38880883, 2024). "Taken together, these data suggested the therapeutic efficacy and low toxicity of PDLIM2-based nanotherapy in the mouse model of refractory lung cancer." (PMID 39718207, 2024). "Concomitant with the downregulation of SDH complex genes, the protein levels of the SDH subunits were diminished in the PDLIM2-downregulated lung cancer cells." (PMID 38880883, 2024). "The synergy was largely blocked when Pdlim2 was genetically deleted from lung cancer cells (ΔSPC), suggesting an important role of PDLIM2 in the combination therapy of chemotherapeutic drugs and anti-PD-1." (PMID 39718207, 2024). "We assessed mitochondrial respiration in both control and PDLIM2-knockdown lung cancer cells by measuring the oxygen consumption rate (OCR) using the Seahorse Mito Stress assay." (PMID 38880883, 2024). "We further examined the correlation between PDLIM2 gene expression and the clinical prognosis of lung cancer patients." (PMID 38880883, 2024). "PDLIM2 repression in human lung cancer involves both epigenetic alteration and genetic deletion, and Pdlim2 genetic deletion in mice leads to development of spontaneous tumors, majorly lung tumors." (PMID 39718207, 2024). "Consistently, elevated levels of ROS and succinate were detected in PDLIM2-knockdown lung cancer cells." (PMID 38880883, 2024). "Since knockdown of PDLIM2 leads to the accumulation of mtROS and succinate, we further investigated the protein levels of HIF-1α and PHD2 in PDLIM2 knockdown lung cancer cells." (PMID 38880883, 2024). "To characterize the potential new lung cancer therapy, we examined the expression levels of PDLIM2 in lung tumors and several organs, including the liver, kidney, and spleen." (PMID 39718207, 2024). "In this study, we investigated the role and functional mechanisms of PDLIM2 in the growth of lung cancer." (PMID 38880883, 2024). "Further experiments in a mouse model of lung cancer demonstrated that it is possible to use nanotechnology to deliver PDLIM2 to cancer cells for effective cancer therapy with low toxicity." (PMID 39718207, 2024). "Combination of PDLIM2 nanotherapy, chemotherapy and immunotherapy shows great efficacy in lung cancer treatment." (PMID 39718207, 2024). "Taken Together, these findings suggest that the alteration in TCA cycle-related genes resulting from PDLIM2 downregulation leads to the accumulation of mtROS, and oncometabolites including succinate in lung cancer cells." (PMID 38880883, 2024). "This reduction in PDLIM2 expression was consistent across all stages of lung cancer, from stage I to stage IV." (PMID 38880883, 2024). "An analysis of TCGA data related to PDLIM2 in lung cancer using the UALCAN database revealed a significant decrease in PDLIM2 mRNA expression in patients at different stages compared to normal tissue." (PMID 38880883, 2024). "In this study, human clinical samples and data were used to investigate PDLIM2 genetic and epigenetic changes in lung cancer." (PMID 39718207, 2024). "To investigate the functions of PDLIM2 in lung cancer cells, we established stable PDLIM2 knockdown LLC and A549 cell lines through the transfection of PDLIM2-targeted shRNAs." (PMID 38880883, 2024). "Consistently, PDLIM2 knockdown in lung cancer cells affected mitochondrial functions, as indicated by the reduction in all the major parameters of the OCR, diminished respiring mitochondria, and increased mitochondrial fission in the cells." (PMID 38880883, 2024). "The expression of PDLIM2 was downregulated in lung cancer, and this downregulation correlated with poor prognosis in patients." (PMID 38880883, 2024). "Further studies revealed that the tumor-promoting effect of PDLIM2 downregulation in lung cancer involves the accumulation of ROS, succinate, and the associated activation of HIF-1α." (PMID 38880883, 2024).
lung carcinoma (continued). "In any case, the results suggest dysregulated mitochondrial function and increased TCA cycle metabolites in the PDLIM2-knockdown lung cancer cells." (PMID 38880883, 2024). "Here, we identify the tumor suppressor PDLIM2 as an intrinsic checkpoint of AMs and monocytes for lung cancer suppression." (PMID 33539325, 2021). "We aimed to determine the significance of PDLIM2 in AMs given its tumor suppressor role in lung cancer and its high expression in AMs." (PMID 33539325, 2021). "Similar to its repression in lung precancerous and cancer cells, PDLIM2 downregulation in myeloid cells and in particular AMs is also an important mechanism promoting lung cancer." (PMID 33539325, 2021). "Treatment using the class I-specific HDAC inhibitor MS-275 or the pan HDAC inhibtor TSA induced PDLIM2 re-expression in human lung cancer cell lines or epithelial cell line transformed by K-RasQ61H oncogenic mutant." (PMID 31757943, 2019). "Consistently, PDLIM2 deletion decreased apoptosis and increased proliferation of lung cancer cells, whereas PDLIM2 re-expression showed opposite effects." (PMID 31757943, 2019). "PDLIM2 was also found to be significantly repressed at both RNA and protein levels in 9 out of 11 human lung cancer cell lines examined." (PMID 31757943, 2019). "PDLIM2 is repressed epigenetically in lung cancers, which are frequently resistant to anti-PD-1/PD-L1 and chemotherapy." (PMID 31757943, 2019). "Compared to normal lung tissues, the expression of PDLIM2 was significantly decreased in human lung cancers." (PMID 31757943, 2019). "Our in vivo mouse model studies showed that PDLIM2 deletion decreased while its expression increased MHC-I in lung cancer cells." (PMID 31757943, 2019). "Analysis of the EMBL-EBI Expression Atlas database revealed that PDLIM2 was expressed at significantly low levels in 212 out of 287 human lung cancer cell lines." (PMID 31757943, 2019). "PDLIM2 repression is thus clinically and pathogenically relevant to human cancers, particularly lung cancer." (PMID 31757943, 2019). "Obviously, survival gene induction by PDLIM2 repression also protects lung cancer cells from chemo-therapeutic drugs." (PMID 31757943, 2019). "More importantly, treatment with the DNMT inhibitor 5-aza-dC led to promoter hypomethylation and re-expression of PDLIM2 in human lung cancer cells." (PMID 31757943, 2019). "Nevertheless, these data suggested that PDLIM2 restoration is essential for the anti-lung cancer activity of 5-aza-dC and MS-275." (PMID 31757943, 2019). "Herein we identify PDLIM2 as a tumor suppressor particularly important for lung cancer therapeutic responses." (PMID 31757943, 2019). "Treatment using 5-aza-dC and MS-275 also restored PDLIM2 expression in murine lung cancers both in vitro and in vivo." (PMID 31757943, 2019). "Conversely, HDAC1 knockdown by shRNAs increased promoter-bound H3K14Ac and PDLIM2 transcription in human lung cancer cells." (PMID 31757943, 2019). "Whereas paclitaxel treatment induced MDR1 expression in lung cancer cells and subsequently drug efflux, PDLIM2 re-expression was sufficient to block paclitaxel induction of MDR1 and drug efflux." (PMID 31757943, 2019). "Here, the authors describe the mechanism through which epigenetic restoration of PDLIM2 synergises with anti-PD-1 and chemotherapy in lung cancers." (PMID 31757943, 2019). "In line with its role in promoting ubiquitination and proteasomal degradation of nuclear RelA and STAT321–23, PDLIM2 deletion increased while its expression decreased nuclear RelA and STAT3, a hallmark of NF-κB and STAT3 activation, in lung cancer cells." (PMID 31757943, 2019). "PDLIM2 deletion increased while its expression decreased expression of cell growth genes, including Bcl-xL and Cyclin D1 in lung cancer cells." (PMID 31757943, 2019).